TLR9 (toll like receptor 9)
Diseases named in the same sentence as TLR9 in open-access papers (continued):
Sharing a sentence is not in itself a finding about the gene and the disease.
colitis (continued). "In addition, the intraperitoneal (ip) administration of immunostimulatory TLR9-agonist DNA sequences protects mice from DSS-induced colitis via the induction of indoleamine 2,3 dioxygenase-1." (PMID 36359370, 2022). "Moreover, a significant upregulation of TLR2 and TLR9 was observed in the group with active colitis." (PMID 35745756, 2022). "On the other hand, activation of TLR9 significantly exacerbated mouse colitis in a different study." (PMID 33381513, 2020). "The authors described that bacteriophages or phage DNA could stimulate IFN-γ production via TLR-9 sensing, resulting in exacerbated colitis." (PMID 33072000, 2020). "Overall, these findings provide evidence that L. johnsonii and B. thetaiotaomicron not only attenuated the development of colitis mediated by TLR9 but were also involved in the elimination of C. glabrata from the gut via chitinase-like and mannosidase-like activities." (PMID 32661259, 2020). "Likewise, it was shown that the activation of TLR9 with the agonist administered prior to the induction of colitis induced anti-inflammatory effects." (PMID 31357438, 2019). "In contrast, overexpression of the NOD2 gene rescued mice from peptidoglycan-induced colitis, and mice deficient in TLR9 and MyD88 no longer demonstrated probiotic-mediated inhibitory effects on intestinal inflammation in experimental colitis." (PMID 29892282, 2018). "Existing literature showed that TLR9 could inhibit inflammatory reaction in adipose tissues, colitis tissues, intestinal tissues, and human lung epithelial cells." (PMID 30662369, 2018). "In TNBS-induced colitis, a significant increase in TLR9 expression was observed." (PMID 26718757, 2015). "TLR9 expression correlates with the extent of inflammation in TNBS-induced colitis." (PMID 26718757, 2015). "Our data showed that treating TNBS-induced colitis with 1,25(OH)D3 could reduce TLR9 expression in the rat colon." (PMID 26718757, 2015). "Therefore, the aim of this study was to investigate the effect of 1,25(OH)D3 on 2,4,6-trinitrobenzenesulfonic acid (TNBS)-induced colitis and TLR9 expression in rats." (PMID 26718757, 2015). "For example, experimental studies in hosts knockout for TLR9, TLR4, and TLR2 have shown increased susceptibility to the development of a colitis induced by dextran sodium sulfate (DSS), as well as the protective role against DSS colitis induced by agonists of TLR2 and TLR4 supplement." (PMID 26090492, 2015). "Because previous studies have shown that TLR9 activation exerts protective effects against the development of colitis we have investigated whether TLR9 activation by in vivo administration of CpG rescues FXR−/− mice from colitis induced by TNBS administration." (PMID 23372731, 2013). "In contrast, activation of FXR rescued TLR9−/− and MyD88−/− mice from colitis." (PMID 23372731, 2013). "Results of these investigations demonstrate that FXR activation effectively rescued TLR9−/− and MyD88−/− mice from colitis induced by TNBS, strionlgly indicating that the FXR signaling pathways lies downstream to TLR9 and MyD88 and is conserved in mice lacking the expression of these genes." (PMID 23372731, 2013). "Also, TLR9-triggered protection against experimental colitis, which reflects bacterial invasion, was IFN-I dependent, and poly(I:C), a strong IFN-I inducer, protected mice against inflammatory bowel disease." (PMID 24244159, 2013). "Likewise, rectal administration of LPS was shown to promote colitis in rabbits, and administration of the TLR9 agonist CpG-ODN enhanced DSS-induced colitis in mice." (PMID 20161736, 2010). "Indeed, it is already demonstrated that TLR9 can trigger anti-inflammatory functions in experimental colitis, and it has been shown that upon TLR-signaling the levels of the anti-inflammatory cytokine IL-10 can be enhanced within dendritic cells." (PMID 18974879, 2008).
colitis (continued). "Activation of TLR9 by subcutaneous injection of agonistic CpG-containing double-stranded DNA (dsDNA) prevents the development of dextran sodium sulfate (DSS)-induced colitis in a type I IFN-dependent manner when TLR9 agonists were administered before colitis induction." (PMID 41155222, 2025). "Collectively, these in vitro and in vivo studies strongly suggest that MDP activation of NOD2 inhibits TLR9-induced type I IFN responses through the removal of the K63-linked polyubiquitination of TRAF3 by OTUD5 activation, and thereby suppresses the development of TLR9-induced colitis." (PMID 41155222, 2025). "Similarly, the expressions of TLR2 and TLR9 were significantly upregulated in DSS-induced colitis." (PMID 35745756, 2022). "Furthermore, it was reported that TLR9 signaling, which was stimulated by orally administered Lactobacillus casei in the intestine of suckling rabbit in present study, had an anti-inflammatory effect on murine experimental colitis." (PMID 31010962, 2019). "The same group went on to show that intestinal inflammation following DSS challenge is reduced in TLR9−/− mice compared with wild-type and that administration of adenoviral ODNs (which blocks the effects of DNA sequences) to wild-type mice with established colitis results in amelioration of disease." (PMID 29515999, 2018). "Thus, we hypothesize that 1,25(OH)D3 could relieve inflammation in TNBS-induced colitis by reducing TLR9 expression." (PMID 26718757, 2015). "Moreover, we demonstrated that the severity of colitis was correlated with TLR9 expression." (PMID 26718757, 2015). "Previous studies have shown that CpG rescues wild type mice from murine colitis, highlighting a role for TLR9 generated signals in repressing intestinal inflammation and activation of TLR9 is instrumental to the immune-regulatory activity of probiotics in rodent models of colitis." (PMID 23372731, 2013). "Apart from these possible epithelial cell-mediated mechanisms we could identify a CpG/TLR9-mediated modulation of T-cell function in the CD4+ T-cell-dependent SCID transfer model of colitis in which colitis is induced in SCID recipients by adoptively transferred CD4+CD62L+ cells." (PMID 21188217, 2010). "Vice versa, TLR9-deficient mice which do not respond to CpG motifs showed a more than 50% reduced chronic intestinal inflammation two months after the induction of chronic dextran sodium sulphate- (DSS-) induced colitis." (PMID 21188217, 2010). "In contrast, when TLR9 was activated by its agonists during the induction of colitis, the activation of type I IFN signaling exacerbated DSS-induced colitis by promoting T helper type 1 responses." (PMID 41155222, 2025). "Our previous findings demonstrate EBV DNA’s significant role in exacerbating colitis symptoms and elevating the levels of the pro-autoimmune cytokine interleukin-17A (IL-17A) in an IBD mouse model via toll-like receptor 9 (TLR9)." (PMID 40722611, 2025). "By being required for TLR9- as well as NOD1-mediated cytokine production, SLC15A4 has been shown to promote Th1-dependent colitis in vivo." (PMID 35562597, 2022). "Campylobacter jejuni disorder the protective toll-like receptor 9 (TLR9) signaling in intestinal epithelial cells and aggravated colitis in mice treated with DSS." (PMID 35634366, 2022). "This study showed that expression of TLR2, TLR4, TLR9, and MyD88 mRNA was significantly increased in colonic tissues of DSS-induced colitis mice relative to the normal control mice." (PMID 33193406, 2020). "TLR-9 and MBL-C expression increased significantly in response to both C. glabrata and colitis, when compared to mice treated with DSS only, although TLR-4 expression decreased." (PMID 29463799, 2018). "After the establishment of experimental colitis, the expressions of TLR2, TLR4, and TLR9 were enhanced in the inflammatory cells which were located in lamina propria and submucosa." (PMID 25276470, 2014).
colitis (continued). "Analysis of mucosal damage score demonstrated that, with the exception of TLR4−/− mice which showed a less severe disease, the severity of the colitis was essentially similar in wild type, TLR2−/−, TLR9−/− and MyD88−/− mice (n = 6; p<0.05)." (PMID 23372731, 2013). "Results of these studies demonstrate that, in comparison with C57BL6 wild type mice, colitis severity was attenuated by TLR4 ablation, while the opposite was observed in TLR9−/− mice." (PMID 23372731, 2013). "One study showed that in dextran sulfate sodium (DSS)-induced colitis, IFN-β offers protective benefits when induced via TLR9 and when administered in recombinant form during the course of colitis, although the effect on IL-17 expression was not reported." (PMID 21365015, 2011). "In addition, it was also shown that the attenuation of DSS colitis could be caused by DNA of the VSL#3 probiotic mixture through TLR9 signaling, and nonviable bacteria were equally effective in reducing inflammation in this model." (PMID 21991534, 2011). "Also noteworthy is the contribution of bacterial DNA and TLR9 signaling in augmenting murine intestinal inflammation supported by our previous studies: In murine intestinal graft-versus-host disease we observed recently that TLR9 is essentially involved in aggravation of colitis." (PMID 21698299, 2011). "TLR9-induced exacerbation of colitis was type I IFN-dependent because colitis in mice lacking the type I IFN receptor was not modified by CpG injection." (PMID 41155222, 2025). "Acute colitis was induced in wild-type (WT), TLR2 knockout (KO), TLR4 KO, and TLR9 KO mice by administrating the mouse pathogen C. rodentium, then colitis severity was evaluated based on body weight changes, pathology, and mucosal cytokine gene expression at two weeks after infection (acute phase)." (PMID 41293152, 2025). "Only TLR9 KO mice developed significant visceral hyperalgesia despite findings indicating mild mucosal inflammation in the acute colitis phase and lack of persistent low-grade inflammation with hyperpermeability in the recovered phase." (PMID 41293152, 2025). "Another experiment on animals showed that nonviable probiotics used the TLR9-Myd88 pathway to counteract dextran sodium sulfate-induced colitis, and their DNA was responsible for the protective benefits." (PMID 37242437, 2023). "For example, Escherichia coli, Lactobacillus plantarum and Bacteroides thetaiotaomicron bacteriophages stimulate interferon-γ production through Toll-like receptor 9 signalling independent of bacteria and E. coli bacteriophages worsen colitis in mice." (PMID 35449461, 2022). "As TLR9 besides other TLRs has been shown to synergize with CD40-signalling in B cells, it is theoretically possible that a strain-specific differential TLR-expression in DCs contributes to the different grades of colitis observed in this study." (PMID 30653608, 2019). "A 16-gene signature (CARD12, CCL3, CCR3, CXCL1, F5, FAM210B, GADD45A, IL18bp, IL2RA, IL5, IL8, MMP9, PTGS2, SOCS3, TLR9 and UBE2C) was identified from 30 days post-tremelimumab initiation blood that discriminated patients developing grade 0–1 from grade 2–4 diarrhea/colitis." (PMID 30227886, 2018). "To investigate whether MIS416, a microparticle comprising NOD2 and TLR9 agonists, could enhance the therapeutic effects of hUCB-MSCs, we co-injected hUCB-MSCs and MIS416 in DSS-induced colitis mice." (PMID 29892282, 2018). "DSS-induced colitis significantly increased TLR-4, TLR-9, and MBL-C expression in colon tissues." (PMID 29463799, 2018). "Still others presented data that TLR9, TLR3, or TLR7 agonists could induce type I IFN, which can prevent experimental colitis." (PMID 29441063, 2018). "DSS-treatment for 8 days resulted in elevated mRNA levels of TLR4 and TLR7, while expression of TLR2 and TLR9 did not change in colitis mice." (PMID 27658624, 2016).
colitis (continued). "On the other hand, bacterial DNA stimulation of IECs via apical TLR9 may result in anti-inflammatory effects, with the inhibition of TNF-α and IL-8 secretion, as well as NFκB activation, reducing colitis severity." (PMID 26925061, 2016). "Therefore, we sought to investigate the role of EBV particles, irrespective of viral replication, on colitis severity and the involvement of TLR9 inhibition in ameliorating intestinal inflammation in an IBD mouse model." (PMID 40722611, 2025). "Both macrophages and DCs in the colon express the integrin CD11c, and depletion of CD11c+ cells using CD11c-DTR mice may reduce or increase colitis severity, depending on the presence or absence of the TLR9 agonist CpG." (PMID 32117307, 2020). "In this study, we investigated whether administration of MIS416, a novel microparticle that activates NOD2 and TLR9 signaling, could enhance the therapeutic efficacy of hUCB-MSCs against Crohn’s disease, using dextran sulfate sodium (DSS)-induced colitis model." (PMID 29892282, 2018). "Our previous study has shown that high expressions of TLR2, TLR4, and TLR9 in the colonic mucosa of experimental colitis rats and a positive correlation between intestinal damage degrees, which implied TLR2, TLR4, and TLR9, prompt the immune injury of murine intestinal in experiment colitis." (PMID 25276470, 2014). "Interestingly, IL-10 and TLR4 double knockout mice have an accelerated colitis development compared to IL-10 and TLR9 double knockout and IL-10 single knockout which do not develop colitis." (PMID 23382912, 2013). "Protection from colitis was seen with VSL3 in TLR2 and TL4 knockout mice but not TLR9 mice validating the role of TLR9 signaling in the probiotic mechanism." (PMID 21995674, 2011). "However, HnAb treatment decreased the mRNA expression of TLR4 and MyD88, but not that of TLR2, TLR9, compared to vehicle-treatment in DSS-induced colitis mice." (PMID 33193406, 2020). "In TNBS-induced colitis group, a moderate correlation was detected between MPO activity and the number of TLR9-positive cells (r = 0.654, P < 0.001) and a low non-significant correlation between MPO activity and TLR9 gene expression (r = 0.394, P = 0.057)." (PMID 26718757, 2015). "However, since in vivo CpG administration failed to rescue FXR−/− from colitis induced by TNBS, it appears that FXR is a non-dispensable component of the immune-modulatory activity of TLR9." (PMID 23372731, 2013).
breast cancer (56 papers, 2010 to 2026). A primary or metastatic malignant neoplasm involving the breast. "Low TLR9 expression in breast cancer tissue is associated with poor prognosis, specifically in TNBC." (PMID 39644451, 2024). "In certain contexts, TLR9 signaling has been associated with tumor-promoting effects in breast cancer." (PMID 38903515, 2024). "Further research is needed to elucidate the mechanisms underlying TLR9 signaling in breast cancer pathogenesis and to explore its potential as a therapeutic target for breast cancer treatment." (PMID 38903515, 2024). "The expression of TLR9 has been associated with poorly differentiated tumors in breast cancer specimens, suggesting a potential role in cancer progression." (PMID 38903515, 2024). "Breast cancer patients with high TLR9 expression by fibroblast-like cells were associated with low probability of metastasis." (PMID 38903515, 2024). "A total of 21 different germline TLR9 variants were detected in the 131 TCGA AA breast cancer cases." (PMID 28886076, 2017). "We also aimed to identify the landscape of germline TLR9 variants in both EAs and AAs, and determine if such variants contribute to AA breast cancer risk." (PMID 28886076, 2017). "Germline TLR9 variants in European Americans (EAs) and AAs were investigated, to determine their contribution to AA breast cancer risk." (PMID 28886076, 2017). "TLR9-activation has been shown to stimulate invasion in glioblastoma, astrocytoma and breast cancer epithelial cells, and also cause differentiation of pulmonary fibroblasts into a myofibroblast phenotype." (PMID 25126740, 2014). "Of the two SNPs we examined in TLR9, only the synonymous coding SNP rs352140 (P545P) was associated with breast cancer risk (OR 0.85, 95% CI 0.74–0.97)." (PMID 23634849, 2013). "Some studies have suggested that TLR9 expression may be associated with specific molecular subtypes of breast cancer, such as triple-negative breast cancer." (PMID 38903515, 2024). "TLR4 and TLR9 signaling have been associated with breast cancer progression due to findings revealing that both LPS and CpG-ODN could promote breast cancer cell migration, invasion and metastatic spreading." (PMID 27187369, 2016). "Finally, in addition to breast cancer, the significance of our finding should be further studied also in other cancers where BPs are much used or where low tumor TLR9 expression is associated with poor outcome, such as renal cell carcinoma." (PMID 27888633, 2016). "In addition to the actual tumor cells, the TLR9 expression status of tumor-associated fibroblast-like cells has also been shown to be of prognostic value in breast cancer." (PMID 25101078, 2014). "Although this study suggested variation in four genes, MAP3K1, MMP9, TANK, and TLR9, may affect the risk of breast cancer, previous studies have observed associations for other genes in TLR or NFκB pathways." (PMID 23634849, 2013). "Therefore, future studies should continue to assess the relationship between polymorphisms in TLR9 and breast cancer risk." (PMID 23634849, 2013). "Similarly, in the 4T1 mammary tumor model, spontaneously metastatic to the lungs, the intra-nasal injection of the TLR9 agonist SD101 causes profound remodeling of the lung microenviroment with dendritic cell expansion and the formation of tertiary lymphoid structures adjacent to lung tumors." (PMID 37365634, 2023). "In this work we demonstrate early response to STING + TLR9 combination immunotherapy in an immunologically cold 4T1 breast cancer (BC) murine tumor model with multiplexed dynamic molecular imaging with surface-enhanced Raman spectroscopy (SERS)." (PMID 41543356, 2026). "Various researches identified that TLR9 pathway is frequently activated in solid malignancies, including breast cancer, colorectal cancer and HCC." (PMID 40038250, 2025). "In summary, TLR9 signaling in breast cancer is complex and context-dependent, exerting both pro-oncogenic and anti-tumor effects." (PMID 38903515, 2024).